ALB (albumin)
Diseases named in the same sentence as ALB in open-access papers (continued):
Sharing a sentence is not in itself a finding about the gene and the disease.
malnutrition (continued). "However, our results—confirmed by multivariate analysis adjusting for serum albumin to eliminate malnutrition as a confounding factor—were able to indicate otherwise." (PMID 30071093, 2018). "Although serum albumin and cBMI may help identify malnutrition at ICU admission, their efficacy has been questioned." (PMID 29652842, 2018). "Factors that may contribute to fatigue in dialysis patients includes anemia, malnutrition, inflammation, creatinine and albumin levels, depression, and sleep disorders." (PMID 30197740, 2018). "Here, we report a rare case of Muehrcke’s lines accompany with normal range serum albumin after chemotherapy, unlike the hypoalbuminemia in most cases, which suggest malnutrition is not the only cause of Muehrcke’s lines." (PMID 30147932, 2018). "Finally, creatinine and albumin, as in previous literature were low in our study as well, and alone are less relevant indicators of malnutrition." (PMID 29643898, 2018). "In addition, the Glasgow prognostic score (GPS) based on serum CRP (an acute-phase response protein) and albumin levels (a typical index of malnutrition) was developed to aid in appreciating the role of leukocytosis." (PMID 30369930, 2018). "The key finding was that, in the absence of inflammation, participants with dual infection had lower levels of both prealbumin and albumin across all BMI categories except in the obese, which may be suggestive of malnutrition." (PMID 30065944, 2018). "When we stratified these patients according to nutritional status evaluated by SGA, the ‘mild to severe malnutrition’ group was significantly older and had more females, lower hemoglobin, serum albumin and creatinine levels, but higher BUN and hs-CRP levels than the ‘good nutrition’ group." (PMID 30552374, 2018). "Therefore, small amounts of fresh erythrocyte suspension and human albumin were infused multiple times to correct the malnutrition and to improve the immunity of the patients." (PMID 29720686, 2018). "Therefore, preoperative malnutrition is an important clinical problem; conventional body mass index (cBMI) and serum albumin level are commonly used as indicators of malnutrition status." (PMID 29545522, 2018). "Serum albumin and conventional BMI (cBMI) are commonly used indices of malnutrition status." (PMID 29545522, 2018). "Regardless of the tool used to diagnose malnutrition, low values of albumin or BMI or low MNA were associated with an increase in mortality." (PMID 29710860, 2018). "The current study found that prealbumin can differentiate between inflammation-induced reduction of albumin and true malnutrition in adults singly or coinfected with HIV and intestinal helminths in the presence or absence of inflammation in various BMI categories." (PMID 30065944, 2018). "The serum albumin level is the most commonly used serological indicator to evaluate malnutrition." (PMID 29506546, 2018). "Moreover, whereas preoperative albumin reflects patient chronic comorbidity and malnutrition status, a drop in postoperative albumin is a marker of surgical stress and can be a predictor of clinical outcomes." (PMID 29880755, 2018). "Therefore, decreased serum albumin level represents a malnutrition status and also a sustained systemic inflammation response." (PMID 29544476, 2018). "Serum albumin is a widely used variable for diagnosis and follow-up of patients with malnutrition." (PMID 28673364, 2017). "Notably, the generation of albumin can be suppressed by malnutrition and inflammation, which are triggers for many cancers." (PMID 28654895, 2017). "Albumin is the most extensively studied proteins for diagnosing malnutrition." (PMID 28771192, 2017). "Still, the extent of albumin loss has to be considered as low albumin levels are associated with negative long-term adverse outcomes due to malnutrition." (PMID 28085888, 2017). "GPS, a combination of CRP and ALB, is an excellent index of system inflammation and malnutrition." (PMID 29100345, 2017).
malnutrition (continued). "This indicates that using albumin with a cutoff of 3.5 g/dL would fail to identify a proportion of the patients diagnosed to be at high risk of malnutrition using NRS-2002, not to mention those at low malnutrition risk." (PMID 28771192, 2017). "This is due to the fact that NRI and malnutrition features were obtained from the albumin level." (PMID 28282392, 2017). "In conclusion, this systematic review confirmed that BMI and several blood biochemicals, including albumin, prealbumin, hemoglobin, total cholesterol, and total protein, are useful biomarkers for adult malnutrition, even with the presence of chronic inflammation." (PMID 28771192, 2017). "The low serum albumin should not be interpreted as a marker of hepatocellular synthetic dysfunction since it is influenced by multiple factors such as malnutrition, chronic infection, chronic inflammation and HIV-associated nephropathy." (PMID 28148232, 2017). "Plasma albumin has often been used as a marker of malnutrition." (PMID 29261657, 2017). "Similar to albumin, serum prealbumin has also been used as a blood marker of malnutrition." (PMID 28771192, 2017). "Besides this, patients with a decrease of > 15% in the pre-albumin level was more likely to be malnourished, perhaps pre-albumin can be an ideal bio-marker for malnutrition(OR = 2.442, p = 0.041, CI [1.036, 5.757])." (PMID 29137377, 2017). "Inflammation and malnutrition reduce the concentration of albumin by decreasing its synthesis rate." (PMID 28866982, 2017). "Malnutrition which might be reflected by serum albumin level could weaken the human defense mechanisms, including anatomic barriers, cellular and humoral immunity, and phagocyte function." (PMID 28978171, 2017). "The criteria of the European Society for Clinical Nutrition and Metabolism 35 demonstrate that low serum albumin levels is an established marker of malnutrition, and improving perioperative nutrition, especially immunonutrition, can result in reduced postoperative complications and hospital stays." (PMID 28925039, 2017). "As expected, subjects with malnutrition had a significantly lower body mass index (BMI; 23.4 ± 6.4 vs. 25.6 ± 7.3; p < 0.001), serum albumin (26.0; 22.1–33.0 vs. 32.5; 25.4–36.3 g/L; p < 0.0001), and were older, as compared to well-nourished patients (73.0 ± 20.0 vs. 54.0 ± 22.3 years; p < 0.0001)." (PMID 28300757, 2017). "Serum albumin may bridge geriatric physical and mental problems in conditions such as frailty, impaired activities of daily living, cognitive decline, and malnutrition." (PMID 27276092, 2016). "In addition, it is well accepted that malnutrition is a predictor of survival in cancer, and serum albumin is considered a nutritional indicator." (PMID 26754834, 2016). "However, in our study, the markers of malnutrition and inflammation, albumin and WBC counts, were found to be similar between MI/CAD and non-MI/CAD group." (PMID 27927204, 2016). "Given that serum albumin levels have been regarded as major markers of either malnutrition or PEWS, the inverse relationship between serum albumin and circulating adiponectin concentrations might be in line with our findings." (PMID 27895721, 2016). "An excessively low preoperative serum albumin levels indicate poor liver function and malnutrition and often indicate a poor tolerance to surgery and unfavorable anastomosis healing, prone to ascites and pancreatic fistula, which were also the main risk factors of PPH." (PMID 27975049, 2016). "For cancer patients, malnutrition and inflammatory responses could suppress the synthesis of albumin by hepatocytes and alter the metabolic homeostasis in the tumor microenvironment." (PMID 27399281, 2016). "Hence, it was concluded that albumin cannot be reliably used as a marker for diagnosing protein-calorie malnutrition." (PMID 27174435, 2016).
malnutrition (continued). "Losses of lean and adipose tissue are inherently linked to many common assessments of malnutrition—such as anthropometric measurements and malnutrition scoring tools that monitor changes in weight—and indirectly with other parameters used for assessment, such as albumin." (PMID 27827911, 2016). "The low albumin level could be indirectly (i.e., by being a marker of the malnutrition–inflammation syndrome) or directly (i.e., as an etiological factor) responsible for this higher risk of infection." (PMID 27218256, 2016). "Another marker of systemic inflammation is albumin which is an acute phase reactant that is influenced by multiple factors mainly including malnutrition and inflammation which may reduce albumin levels irrespective of the patient's nutritional status." (PMID 27433355, 2016). "Malnutrition, based on low albumin concentration, was relatively rare among respondents examined." (PMID 27794563, 2016). "Albumin represents a marker of nutritional status and hypoalbuminemia might reflect malnutrition or declining health status." (PMID 25924723, 2015). "When using the hypoalbuminemia criterion of serum albumin levels less than 3.5 g/dl, the prevalence of malnutrition in most common cancers ranged from 4 to 28 %, which was higher than the rates of malnutrition computed by body weight loss or underweight BMI status." (PMID 26345703, 2015). "Age, albumin, and body mass index might reflect malnutrition, frailty, insufficient diet, and other comorbidities." (PMID 26618538, 2015). "On the other hand, malnutrition and inflammation can suppress the synthesis of albumin." (PMID 24718309, 2014). "Albumin synthesis is suppressed in response to inflammatory conditions and malnutrition." (PMID 25074590, 2014). "Elevated level of serum albumin is related to haemoconcentration and reduced level is associated with malnutrition, chronic inflammatory diseases representing a negative acute phase protein." (PMID 23565300, 2013). "Malnutrition (albumin < 35 G/L) was also found to be related with CMV recent infection (P = 0.031)." (PMID 23374225, 2013). "Some biochemical parameters (e.g. serum albumin) and anthropometric measurements (e.g. body weight) are effective in identifying the patients with malnutrition, however, they have some limitations affected by some non- nutritional factors, such as edema, liver disease, and chronic inflammation, etc." (PMID 23825573, 2013). "Serum albumin is the most extensively used method to measure malnutrition in CKD patients." (PMID 28197445, 2013). "A recent retrospective study of 200 patients suggested that serum albumin at admission and total lymphocyte count could serve as markers of malnutrition and could be used to predict clinical outcome after hip fractures." (PMID 22248167, 2012). "Low serum albumin level has been regarded as indicator of malnutrition." (PMID 21860616, 2012). "In summary, we have found that malnutrition, defined by the WHO standard of low BMI, is common in Rwandan women, independent of HIV status, but that no measure of nutritional status in our cohort was systematically associated with serum albumin." (PMID 22532840, 2012). "A Cox regression analysis, which considered patient age, presence of DM, initial serum albumin levels, seroconversion after HBV vaccination, dialysis modality, and gender, showed that advanced age and malnutrition were associated with increased mortality (P = 0.035 and P = 0.032, respectively)." (PMID 22935561, 2012). "Among biochemical markers albumin level is most frequently used in malnutrition assessment." (PMID 22574625, 2012). "We also discovered that low serum albumin level was associated with low 25-OHD level, which might be explained not only by malnutrition or uremic inflammation but also by the positive correlation between serum albumin and vitamin D binding protein levels." (PMID 22533967, 2012).
malnutrition (continued). "The serum albumin concentration is a marker of nutritional status; these patients may have been suffering from malnutrition, which could explain these indeterminate results." (PMID 21501477, 2011). "Low albumin level means protein-calorie malnutrition to some extent." (PMID 21600038, 2011). "In this analysis, we describe relationships between pre-treatment levels and post-ART changes in serum phosphate, albumin, ferritin and CRP and the risk of mortality in the first 12 weeks of ART in a cohort of adults in sub-Saharan Africa with advanced malnutrition and immunosuppression." (PMID 21477359, 2011). "As for serum albumin levels, there is one simple question if dietary protein intake is associated with serum albumin levels in a general population without extreme malnutrition." (PMID 20351474, 2010). "Serum albumin level can be lowered by decrease in synthesis (cirrhosis or some inflammatory diseases), leakage outside the body (nephrotic syndrome, severe burns or protein-losing enteropathy), or malnutrition." (PMID 20351474, 2010). "In the later stages of disease, malnutrition and inflammation suppress albumin synthesis." (PMID 21176210, 2010). "Malnutrition is very common in patients with liver cirrhosis, especially in the protein-calorie malnutrition, which has many clinical features, such as thin, anemia, immunological function disorder, and decreased serum albumin, even the ascites and abdominal infection." (PMID 27942305, 2010). "Our data show that the both the Noveliver and the compound pollen protein nutrient increase the serum albumin and ameliorate malnutrition in cirrhotic rats; the recovery of serum albumin might be related to the hepatic damage repair and liver regeneration." (PMID 27942305, 2010). "Liver function tests exposed a reduced albumin level (2.1 g/dL = 21 g/L), consistent with the diagnosis of malnutrition that was evident from patient's general cachectic appearance (weighing only 43 kg), and history of reduced caloric intake and recent weight loss." (PMID 20062665, 2009). "The decline of serum albumin is certainly a late phenomenon in terms of malnutrition." (PMID 17980023, 2007). "However, as the disease progressed and EF dropped below 20%, a lower level of albumin (hypoalbuminaemia) became common among patients due to the combined effects of chronic inflammation, fluid overload, and malnutrition, reducing its discriminative power between strata." (PMID 41596354, 2026). "Therefore, we believe CRP should be interpreted with caution, and contemporary nutritional indices—such as the CRP-to-albumin ratio (CAR) or the CRP-to-prealbumin ratio (CPR)—should be incorporated into the assessment of malnutrition in critically ill patients." (PMID 41515189, 2025). "It’s worth noting that our multivariate analysis, unlike the univariate analysis, revealed a protective effect of being in need of help in daily activity and having a low albumin level against developing malnutrition (Exp (B) <1, 95%CI <1), which might seem counterintuitive." (PMID 39854402, 2025). "Furthermore, low serum albumin levels, another characteristic of frailty, indicates malnutrition." (PMID 40777144, 2025). "We acknowledge that serum albumin is a non-specific marker and may be influenced by chronic diseases, protein loss, or malnutrition." (PMID 40710030, 2025). "Moreover, decreased albumin levels reflect acute malnutrition and heightened inflammation." (PMID 41229545, 2025). "While C-reactive protein (CRP)-to-prealbumin and CRP-to-albumin ratios may enhance the predictive value of individual biomarkers for mortality and severe disease-related malnutrition, their limited standalone accuracy underscores the need for further studies and combined clinical interpretation." (PMID 41036189, 2025).
malnutrition (continued). "Notably, the inclusion of inflammation as a diagnostic criterion for malnutrition according to the GLIM criteria may have influenced our results, as inflammatory mediators are major regulators of both hemoglobin and albumin levels." (PMID 41305594, 2025). "Similarly, low albumin levels, indicative of malnutrition, were significant predictors." (PMID 39851480, 2025). "Additionally, we did not account for other aetiologies influencing albumin levels, such as gastrointestinal loss, advanced liver disease, and severe malnutrition." (PMID 40757132, 2025). "In the multivariable beta regression model, malnutrition remained a significant and independent predictor of a higher proportion of time spent in relative intraoperative hypotension (P < 0.001), even after adjusting for age, sex, albumin, CRP, and other relevant covariates." (PMID 41257946, 2025). "Similarly, the analysis of albumin levels in the blood showed a relationship with malnutrition." (PMID 40094974, 2025). "However, the linear regression analysis in this study revealed that malnutrition, prealbumin, and albumin were not independently associated with the elevated ECW/TBW in tumor patients." (PMID 40842552, 2025). "Therefore, TG/HDL-C and serum albumin might represent complementary components of the malnutrition–inflammation–atherosclerosis complex contributing to cardiovascular risk in HD patients." (PMID 41283273, 2025). "Moreover, factors such as malnutrition, malabsorption, and gastrointestinal losses may also lead to reduced albumin concentrations." (PMID 41154492, 2025). "Similarly, decreased levels of hemoglobin and albumin, which were significant in univariate analysis, may reflect chronic inflammation, malnutrition, or bone marrow suppression commonly observed in patients with bacteremia." (PMID 40792110, 2025). "Furthermore, albumin, a component of the GNRI, is an antioxidant, and malnutrition with low albumin levels increases oxidative stress, which may promote atherosclerosis." (PMID 39446306, 2025). "Serum albumin levels were low at 3.04 ± 0.54, which may reflect malnutrition or chronic disease." (PMID 40151482, 2025). "Furthermore, vitamin D3 and albumin levels were possible key markers of malnutrition." (PMID 40863037, 2025). "The findings indicated that albumin concentrations remained within the normal range until patients reached severe states of malnutrition (BMI < 12 or starvation duration exceeding six weeks), at which point clinical manifestations of malnutrition were already apparent." (PMID 40161084, 2025). "The calculation of GNRI involves weight, height, and serum albumin levels, with the value range reflecting the patient's nutritional status, such as 97.5–100 indicating mild malnutrition, 83.5–97.5 indicating moderate malnutrition, and <83.5 indicating severe malnutrition." (PMID 40880745, 2025). "Furthermore, factors such as low albumin due to malnutrition or widespread metastatic disease in advanced cancer patients may also affect the development of cerebral edema." (PMID 40797386, 2025). "In addition, our study analyzed several modalities to evaluate malnutrition and highlighted that poor nutrition (reflected by low albumin and cholesterol, low anthropometric measures, low adiposity on BIA, and low MNA and GNRI scores) correlated with albuminuria." (PMID 40566551, 2025). "Based on the GNRI score, patients with malnutrition risk, when compared to those without malnutrition risk, were older and had lower BMI, lymphocyte count, total cholesterol, triglycerides, low-density lipoprotein, high-density lipoprotein, albumin, and estimated glomerular filtration rate." (PMID 40606134, 2025). "Moreover, albumin synthesis is suppressed by malnutrition and inflammation." (PMID 38730986, 2024).